IGFBP5 (insulin like growth factor binding protein 5)
Diseases named in the same sentence as IGFBP5 in open-access papers (continued):
Sharing a sentence is not in itself a finding about the gene and the disease.
glioma (15 papers, 2017 to 2024). A benign or malignant brain and spinal cord tumor that arises from glial cells (astrocytes, oligodendrocytes, ependymal cells). "The Kaplan-Meier curves demonstrated that high expression of IGFBP5 was remarkably associated with poor OS in all the four datasets, suggesting high IGFBP5 expression can be an independent risk factor to predict the prognosis of glioma patients." (PMID 38164271, 2024). "IGFBP3 and IGFBP5 were overexpressed in gliomas and were associated with higher tumor grade and lower survival." (PMID 35992105, 2022). "By studying the human glioma tissues, we find that IGFBP5 expression associate to the histopathological classification and highly expressed in GBM." (PMID 32127912, 2020). "IGFBP5 was identified as the top upregulated gene in invasive vs non-invasive GSCs that was significantly associated with the poor prognosis of patients with glioma." (PMID 36949068, 2023). "Our results indicated that higher expression of IGFBP5 was associated with a reduction of B and NK cells in glioma, and that less either B or NK cells could activate antitumor immune response and induce immune escape, which in turn, contributed to poor prognosis." (PMID 38164271, 2024). "Collectively, IGFBP5 expression is upregulated in glioma and gradually increases with the progress of tumor grade." (PMID 38164271, 2024). "Consistent with the bioinformatics results, IHC analysis of tissue microarray demonstrated that IGFBP5 expression was highly expressed in glioma." (PMID 38164271, 2024). "Cox and univariate analysis revealed that IGFBP5 expression was positively correlated with age, grade, primary therapy outcome, IDH mutation status, and poor OS in glioma patients." (PMID 38164271, 2024). "Using data from the TCGA, GTEx, Rembrand and Gravendel datasets, we further found that IGFBP5 expression was upregulated in glioma compared to normal tissues." (PMID 38164271, 2024). "To explore the role of IGFBP5 in glioma cells, we examined the expression levels of IGFBP5 in one human astrocyte cell line, HEB, and four human glioma cell lines, SHG44, U251, U87, T98." (PMID 38164271, 2024). "We already verified that IGFBP5 expression was correlated with immune infiltration in glioma through bioinformatics assay." (PMID 38164271, 2024). "In summary, the findings of this study show that IGFBP5 expression is increased in glioma tissues and that its high expression correlates with malignant progression of glioma." (PMID 38164271, 2024). "Collectively, these data discourse that IGFBP5 expression promotes glioma cell migration and invasion." (PMID 38164271, 2024). "IGFBP5 affected glioma cell proliferation, migration, and invasion probably involved in the epithelial-to-mesenchymal transition (EMT) and Hippo-YAP signaling pathway." (PMID 38164271, 2024). "We used the ESTIMATE algorithm to obtain correlations between the expression of IGFBP5 and the immune score (ImmuneScore, StromalScore and ESTIMATEScore) in glioma on data from the TCGA database." (PMID 38164271, 2024). "In these immunostimulators genes, CXCR4, CXCL12 belonged to Chemokines and chemokine receptors, were also positively correlated with IGFBP5 expression in glioma." (PMID 38164271, 2024). "Subsequently, our results show that IGFBP5 expression has positively correlated with the infiltration of immune cells in glioma, including TAM and M2 macrophages." (PMID 38164271, 2024). "Univariate Cox analysis showed that age, gender, WHO grade, IDH mutation status, Primary therapy outcome, 1p/19q deletion status, and IGFBP5 expression were closely correlated with the prognosis of glioma in TCGA dataset." (PMID 38164271, 2024). "In the glioma cells, knockdown of IGFBP5 leads to less proliferating, migrating and invading activities, while overexpression has the opposite effect." (PMID 38164271, 2024). "Our results showed that IGFBP5 expression was significantly and positively correlated with levels of macrophages in glioma." (PMID 38164271, 2024).
glioma (continued). "Immunohistochemistry staining, CCK8, colony formation, scratch and transwell assays and western blot were used to interrogate the expression and function of IGFBP5 in glioma." (PMID 38164271, 2024). "The data also showed that patients with highly-expressed IGFBP5 had worse prognosis than those with lower levels in glioma." (PMID 38164271, 2024). "The results indicated that IGFBP5 expression was significantly and positively correlated with the ImmuneScore, StromalScore and ESTIMATEScore (all P < 0.01) in glioma." (PMID 38164271, 2024). "To explore the functions and pathways affected by IGFBP5, we identified genes positively or negatively co-expressed with IGFBP5 using TCGA data in glioma." (PMID 38164271, 2024). "In glioma, a previous study revealed that IGFBP5 promoted cell invasion involved in EMT, but inhibited cell proliferation." (PMID 38164271, 2024). "The results showed that IGFBP5 expression was significantly correlated with most biomarkers in different types of immune cells in glioma." (PMID 38164271, 2024). "To evaluate the relationships between IGFBP5 expression and immune-related genes in glioma, we performed an integrative analysis to investigate co-expression of IGFBP5 and immunomodulators (immunoinhibitors, immunostimulators and MHC moleculars)." (PMID 38164271, 2024). "To clarify the protein expression of IGFBP5 in glioma, we firstly used the UACLAN database, which is a comprehensive, interactive web resource for analyzing cancer OMICS data." (PMID 38164271, 2024). "Using the TCGA, CGGA, Rembrandt, and Gravendeel datasets, we investigated the predictive potential of IGFBP5 on the prognosis of glioma patients." (PMID 38164271, 2024). "The analysis shows that in glioma patients who had high levels of IGFBP5 expression, the levels of T cell CD4+ memory cells, Neutrophil cells, B cell memory cells, Macrophages, Tregs, and NK cell resting cells significantly increased." (PMID 38164271, 2024). "Immune checkpoint genes such as PD-L1, PD-1, CTLA4, LAG3, HAVCR2, PDCD1LG2 were positively correlated with IGFBP5 in glioma." (PMID 38164271, 2024). "To analyze the correlation between the IGFBP5 expression levels and Clinical parameters, we used the R package to analyze the samples of the glioma cohort TCGA database." (PMID 38164271, 2024). "Here, our study indicates the prognostic implications of IGFBP5 in glioma by data mining of datasets from CGGA and TCGA, Rembrandt and Gravendeel databases." (PMID 38164271, 2024). "It was shown that IGFBP3, IGFBP5, and IGFBP7 were highly expressed in glioma and were associated with higher tumor grade and poorer survival, consistent with our study." (PMID 35992105, 2022). "Genes common to the top 5 activated pathways include POSTN, MMP9, CEBPB, CEBPD, and IGFBP5, which reportedly participate in glioma growth, invasion, and immunosuppression." (PMID 35814469, 2022). "The results from the Oncomine database showed that IGFBP2, IGFBP3, IGFBP4, and IGFBP5 were expressed at a higher level in tissues from patients with brain and CNS cancer than in normal tissues from healthy individuals." (PMID 35832140, 2022). "Based on the data from the Oncomine database, the transcriptional levels of IGFBP2, IGFBP3, IGFBP4, and IGFBP5 were observed to be elevated in brain and CNS cancer." (PMID 35832140, 2022). "And the database show that high expression of IGFBP5 in glioma or recurrent glioma resulted in poor prognosis." (PMID 32127912, 2020). "Taken together, these findings suggest that IGFBP5 is positively correlated with the progression of glioma." (PMID 32127912, 2020). "In order to analyze the expression of IGFBP5 in glioma, we stained of human glioma tissues with antibodies against IGFBP5, and the results indicated that IGFBP5 clinically correlated with the progression of glioma." (PMID 32127912, 2020).
glioma (continued). "Therefore, CIBERSORT, EPIC, quanTiseq and ssGSEA were used to investigate the correlation between IGFBP5 expression and infiltration of immune cells in glioma." (PMID 38164271, 2024). "To further confirm whether IGFBP5 was an independent prognostic factor in glioma patients, we conducted univariable and multivariable Cox regression analysis used the TCGA dataset through 'forestplot' R package." (PMID 38164271, 2024). "Nonetheless, the distinct roles of IGFBP5 in glioma, particularly in relation to molecular mechanisms, tumor microenvironment and immune status, remain unclear." (PMID 38164271, 2024). "To explore the underlying molecular mechanisms, we examined whether EMT and MMP-2, which are recognized as important factors of glioma invasion 11, 12, were involved in IGFBP5-mediated promotion of glioma cell growth." (PMID 38164271, 2024). "Based on our and previous findings, IGFBP5 may be one of the candidate-oncogenes for a diagnosis of poor prognosis in patients with glioma." (PMID 38164271, 2024). "Especially, in vitro assays indicate that IGFBP5 regulates the expression of PD-L1 in glioma." (PMID 38164271, 2024). "According to cox and univariate analysis, a nomogram was constructed to further predict the probability of 1-, 3-, and 5-year OS and the results showed that the sum scores calculated by IGFBP5 expression for each glioma patient could be used to predict OS." (PMID 38164271, 2024). "Overall, our findings suggest that IGFBP5 is strongly involved in glioma development, and may serve as a potential prognostic biomarker and immunotherapeutic target for patients with glioma." (PMID 38164271, 2024). "Few functional and immune insights into IGFBP5 in glioma have been provided in previous studies." (PMID 38164271, 2024). "Furthermore, immunohistochemical staining of tissue microarray and IHC score were used to analyze the expression of IGFBP5 and revealed that expression of IGFBP5 increased in glioma tissues compared with that in normal brain tissues." (PMID 38164271, 2024). "The aim of the present study was to analyze whether IGFBP5 could be used as a predictor of prognosis and immune infiltration in glioma." (PMID 38164271, 2024). "Assessment of the prognostic value of IGFBP5 expression in glioma patients subgrouped by age (age < 60, age ≥ 60), gender (female, male), IDH mutation status (mutant, wild type), WHO grade (WHO 2, WHO 3 & WHO 4), and primary therapy outcome (PD, SD, PR, and CR) was conducted." (PMID 38164271, 2024). "The findings show that elevated IGFBP5 expression increases malignant degree of glioma and results in a worse prognosis for patients, further confirming that IGFBP5 may be an oncogene of glioma." (PMID 38164271, 2024). "All the results suggest the appreciable reliability of IGFBP5 as biomarker for glioma prognosis." (PMID 38164271, 2024). "The analysis showed that strong correlations were shown between IGFBP5 and immune checkpoints, suggesting that IGFBP5 could serve as a immunotherapeutic target for glioma." (PMID 38164271, 2024). "Therefore, the exact function and detailed mechanism of IGFBP5 in regulating the cell invasion and tumor microenvironment in glioma is required for further research." (PMID 38164271, 2024). "Given the potential involvement of IGFBP5, ETV5, and FBXW9 in the invasive potential of GSCs, we subsequently aimed to identify associations between the expression of these three genes and patient survival using TCGA glioma datasets." (PMID 36949068, 2023). "In addition, 5 hub genes in hub network 2 were related to the poor prognosis of gliomas, including F5, IGFBP5, TNC, SCG3, and IGFBP3." (PMID 35387222, 2022). "Consistent with our speculate, recurrent glioma expressed a higher level of IGFBP5 than primary glioma." (PMID 32127912, 2020). "Furthermore, the Chinese Glioma Genome Altas (CGGA) database show that IGFBP5 is significantly increased in recurrent glioma and it predicted worse survival." (PMID 32127912, 2020).
glioma (continued). "Then, cck-8 assay was performed and the results showed that inhibition of IGFBP5 could significantly reduce the cell viability of glioma cell lines U251 and U87, whereas IGFBP5 overexpression dramatically promoted cell proliferation and colony formation in U251 cell lines." (PMID 38164271, 2024). "Furthermore, the AUC values of 1-, 3-, and 5-year predicted survival rates suggested that IGFBP5 may be a potential factor for predicting poor prognosis in glioma." (PMID 38164271, 2024). "Thus, in contrast to its role in other types of cancer, IGFBP5 may serve as an oncogene by activating ROR1/HER2-CREB signaling axis in glioma." (PMID 36949068, 2023). "We further examined IGFPB5 expression in different histology of glioma in four datasets and the data revealed that GBM had the higher expression level of IGFBP5 than other histology types." (PMID 38164271, 2024). "The results revealed that IGFBP5 expression was positively correlated with most immunosuppressive genes, immunostimulators, and MHC genes in glioma." (PMID 38164271, 2024). "The proportion of 22 types of immune cells in glioma samples retrieved from TCGA database was sorted and analyzed by CIBERSORT algorithm to explore the relationship between IGFBP5 expression and tumor immune microenvironment." (PMID 38164271, 2024). "IGFBP5 has also been reported to increase cell invasion and inhibit cell proliferation by EMT in the human glioma tissues." (PMID 38318192, 2024). "The results showed that the expression level of IGFBP5 was the lowest in normal astrocytes (HEB), but significantly higher in glioma cell lines." (PMID 38164271, 2024). "We found that IGFBP5 was significantly elevated in both LGG and GBM, so we subsequently focused on the function of IGFBP5 in glioma." (PMID 38164271, 2024). "Moreover, IGFBP5 may modulate the infiltration of immune cells in glioma microenvironments." (PMID 38164271, 2024). "We further found that a strong link between IGFBP5 expression and immunosuppressive genes, MHC genes, immunostimulator genes in glioma." (PMID 38164271, 2024). "By analyzing the patient survival rates in TCGA glioma datasets, we elucidated the clinical significance of the regulation of ETV5 and FBXW9 by IGFBP5." (PMID 36949068, 2023). "Using the polymerase chain reaction, GBM cell lines were found to express mRNA for IGFBP genes: IGFBP-1 in 42%, IGFBP-2 in 65%, IGFBP-3 in 97%, IGFBP-4 in 3%, IGFBP-5 in 74%, IGFBP-6 in 94%, and IGFBP-7 in 87% of glioma cell lines." (PMID 35832140, 2022). "IGFBP-3, IGFBP-4 and IGFBP-5 transcripts are significantly higher in GBM compared to low-grade gliomas or normal samples, supporting their role in the pathogenesis of gliomas." (PMID 33604294, 2020). "Then, we used WB to examine whether IGFBP5 inhibition or overexpression could mediated PD-L1 and CXCR4 expression in glioma cells." (PMID 38164271, 2024). "Furthermore, we investigated the correlation between IGFBP5 expression and PD-L1, CXCR4 expression in glioma using the CGGA and TCGA databases and the results showed IGFBP5 expression was positively correlated with PD-L1 and CXCR4 expression." (PMID 38164271, 2024). "The present study assesses the expression and biological roles of IGFBP5 in databases of patients with glioma and cultured cells, not in vivo." (PMID 38164271, 2024). "Moreover, our study further demonstrates IGFBP5 participates in proliferation and invasion involved in EMT and Hippo-YAP signaling pathway in glioma cells, and influences the expression of PD-L1 and CXCR4 expression." (PMID 38164271, 2024). "To study the correlation between IGFBP5 expression and WHO grade for glioma, we analyzed the data from TCGA, Rembrand, Gravendeel and CGGA cohorts and the results discoursed that IGFBP5 expression was gradually increased responding to tumor grade through II-IV in these four datasets." (PMID 38164271, 2024).
glioma (continued). "Glioma patients with high ETV5 or FBXW9 expression experienced worse survival than those with low expression, and high IGFBP5 expression in combination with high ETV5 or FBXW9 expression was significantly associated with the worst survival rate among all the groups." (PMID 36949068, 2023). "Since IGFBP5 can promote GBM cell invasion, we speculated that recurrent glioma IGFBP5 expression levels should be higher than primary glioma." (PMID 32127912, 2020). "In addition, we investigated co-staining of dormancy markers EphA5, IGFBP5 and H2BK with selected neural and embryonic stem cell markers that we and others have previously shown to be relevant in gliomas." (PMID 29296224, 2017). "Specifically, we found that, as IGFBP5 levels increased, the expression of the seven immune checkpoint genes (BTLA, CD274, CTLA4, HAVCR2, LAG3, PDCD1, and PDCD1LG2) were increased and a large positive correlation was observed between IGFBP5 and these immune checkpoints in glioma." (PMID 38164271, 2024). "The functions of IGFBP5 in the TME have not been reported in glioma." (PMID 38164271, 2024). "Therefore, the increase ETV5 and FBXW9 expression in response to IGFBP5 has a negative impact on the survival of patients with glioma." (PMID 36949068, 2023). "This does not mean that DRP2, IGFBP5, KLF10, ARHGAP11A and NRP2 are not essential genes for glioma pathogenesis, given the missing data and limited sample size we found." (PMID 34434651, 2021). "Initially, we determined the basal mRNA and protein expression of EphA5, IGFBP5 and H2BK in human non-stem glioma cell lines (A172, LN229 and U251MG) and several GBM primary cultures (basal expression of stem cell markers has been described by our group before)." (PMID 29296224, 2017).